FOXA2 (forkhead box A2)
Diseases named in the same sentence as FOXA2 in open-access papers (continued):
Sharing a sentence is not in itself a finding about the gene and the disease.
hypopituitarism (6 papers, 2020 to 2025). A condition of diminution or cessation of secretion of one or more hormones from the anterior pituitary gland. "Follow-up of all these patients is therefore warranted to examine whether they go on to develop similar features to those reported in individuals with FOXA2 coding variants, particularly (pan)hypopituitarism." (PMID 38605124, 2024). "Studying the signaling pathways affected by the heterozygous loss of FOXA2, as well as identifying the upstream and downstream protein partners of FOXA2, may allow an understanding of how FOXA2 haploinsufficiency leads to GH deficiency and hypopituitarism." (PMID 32277595, 2020). "Additional single case reports described patients with hypopituitarism and HH, and variable other abnormalities, who carried de novo FOXA2 mutations." (PMID 37065762, 2023). "A further gene recently likely associated with HI is the developmental transcription factor, forkhead box A2, FOXA2, in which a de novo heterozygous mutation was found by WES in a child with HI, hypopituitarism, liver, lung and gastrointestinal malformations, choroidal coloboma and dysmorphisms." (PMID 35422763, 2022). "The three individuals (Patients 2, 3 and 5) whose deletion did not extend over the coding region of FOXA2, had not been identified with pituitary hormone deficiencies by the median age of 7 years (range 3–12) but had subtle facial features and developmental delay." (PMID 38605124, 2024).
Infertility (6 papers, 2016 to 2025). "It has been shown that loss of Foxa2 prior to pubertal onset results in infertility due to loss of uterine glands, whereas loss of Foxa2 in the adult results in maintenance of the uterine gland morphology but still loss of fertility due to lack of the GE expression of the cytokine LIF33." (PMID 30356064, 2018). "Knockout of Foxa2 in post-implantation uterine glands using this Cre model led to complete infertility after the first pregnancy, revealing the critical role of Foxa2 in gland function and fertility." (PMID 40149986, 2025). "Mice with uterine‐specific FOXA2‐deleted are completely infertile." (PMID 40117172, 2025). "The FOXA2-deficient mouse was infertile due to defects in embryo attachment and a lack of LIF expression on day 4 of pregnancy." (PMID 37108290, 2023). "Conditional knockout of Foxa2 or Wnt7a with PgrCre/+ mice leads to infertility with no signs of implantation." (PMID 39364135, 2024). "Thus, it would be interesting to determine if intraperitoneal injections of recombinant Lif can rescue infertility of glandless mice, such as PUGKO and aglandular Foxa2 conditional knockout mice." (PMID 27905495, 2016). "However, the infertility observed in adult mice was due to the absence of LIF, which is secreted by the glands, making it difficult to explore the role of Foxa2 in pregnancy." (PMID 40149986, 2025).
liver disease (6 papers, 2012 to 2022). "In the present study, we identify a liver cirrhosis TF—miRNA—mRNA network containing 49 TFs, many of which have been previously implicated in liver disease (e.g. ETS1, FOS, FOXP3, FOXA2, and GATA2)." (PMID 28355233, 2017). "Thus, clarifying the effects of FOXA2 in HSCs in the future would expand understanding of liver diseases." (PMID 29138513, 2017). "Thus, this study was conducted to verify whether human Foxa2 (hFoxa2) overexpression in rat MSC (rMSC) could protect the liver from hepatic diseases by stimulating tissue regeneration after cell transplantation." (PMID 22432472, 2012). "As an autologous stem cell approach, this study was conducted to assess whether forkhead box A2 (Foxa2) gene overexpression in bone marrow-derived mesenchymal stem cells (MSC) could protect the liver from hepatic diseases by stimulating tissue regeneration after cell transplantation." (PMID 22432472, 2012).
oral cancer (6 papers, 2021 to 2024). "It is worth noting that several of the functional partners including CTNNB1, SHH, FOXA2, and SOX2 have been reported to be involved in the progression of oral cancer or linked with the stem cell phenotype of oral cancer cells." (PMID 38304730, 2024). "MRE11 knockdown in oral cancer cells led to increased expression of FOXA2, which was blocked by cotreatment with SC79, an AKT activator." (PMID 33927349, 2021). "A negative correlation between MRE11 and E-cadherin expression and a positive correlation between FOXA2 and E-cadherin (a downstream effector of FOXA2) expression were also observed in oral cancer tissues." (PMID 33927349, 2021). "We found that the expression levels of FOXA2 were downregulated in long‐term arecoline‐treated oral cancer cells." (PMID 34378866, 2021). "Similarly, transcription factor Forkhead Box protein A2 (FOXA2) binding to the CDH1 promoter caused a high expression of E-cadherin and reduced cancer cell migration in oral cancer." (PMID 35563709, 2022). "Forcing FOXA2 expression inhibited, whereas silencing FOXA2 expression promoted FTO expression in oral cancer cells, proving that FTO is negatively regulated by FOXA2." (PMID 34378866, 2021). "We also observed a negative correlation between the expression of MRE11 and FOXA2 in both oral cancer tissues and metastatic lymph nodes, and a negative correlation between the expression of S473 phospho-AKT and FOXA2." (PMID 33927349, 2021).
seminoma (6 papers, 2016 to 2026). A radiosensitive malignant germ cell tumor found in the testis (especially undescended), and extragonadal sites (anterior mediastinum and pineal gland). "Upon loss of SOX2 and FOXA2, TCam-2 maintained a seminoma cell fate for at least twelve weeks, demonstrating that both factors are key players in the reprogramming to an EC-like cell fate." (PMID 31130628, 2019). "An interesting candidate gene is FOXA2, which is up‐regulated during the differentiation of TCam‐2 into a mixed non‐seminoma and was predicted to interact with many differentiation markers, such as AFP, HAND1 and EOMES42." (PMID 28244655, 2017). "Therefore, while it is striking that the prevalence of AFP elevations in the cohort described is similar to the ~ 5% prevalence of FOXA2-positive seminomas reported in prior studies, it is difficult to ascribe the patterns observed to this mechanism." (PMID 39934683, 2025). "Furthermore, TCam-2-ΔSOX2/FOXA2 derived tumors stained positive for pluripotency and seminoma markers OCT3/4, SOX17, TFAP2C, and PRDM1/BLIMP1, but were negative for the differentiation-markers AFP and EOMES." (PMID 31130628, 2019). "So far, the factors / events triggering up‐regulation of FOXA2 during the differentiation of TCam‐2 into a mixed non‐seminoma are unknown." (PMID 28244655, 2017). "Consequently, TCam‐2 cells deficient for SOX2 and FOXA2 were not able to differentiate into non‐seminoma‐like cells at all." (PMID 33448076, 2021). "Thus, FOXA2 might be an important factor in promoting differentiation of the TCam-2-ΔSOX2 cells into a mixed non-seminoma." (PMID 27283990, 2016). "We propose that in ECs, seminomas and PGCs, SOX17 is able to switch from a pluripotency‐promoting to a differentiation‐inducing factor upon microenvironment‐triggered FOXA2 induction, driving differentiation into YST lineage." (PMID 33448076, 2021). "In our study, we highlight FOXA2 as a key driver of p/aYST formation acting in concert with SOX17, which already has been found up‐regulated in p/aYSTs versus seminomas." (PMID 33448076, 2021). "We suggested previously that during in vivo differentiation of TCam‐2 cells into a non‐seminoma including aYST‐like structures, SOX17 switches function from pluripotency‐promoting to differentiation‐inducing as a result of FOXA2 up‐regulation." (PMID 33448076, 2021). "Our results establish FOXA2 (in addition to SOX2) as an essential factor driving reprogramming and differentiation of seminoma-like TCam-2." (PMID 31130628, 2019). "Our results further strengthen the idea that seminomas show a plasticity, which is influenced by the microenvironment and regulated by SOX2 and FOXA2." (PMID 31130628, 2019). "Additionally, FOXA2 was sensitive enough to detect few YST cells in bulk tumour masses, like classical seminomas with elevated serum AFP levels, which has an important implication for clinical use; i." (PMID 33448076, 2021). "Next, we confirmed that SOX2- and FOXA2-deficient TCam-2 cells do not differ from the parental TCam-2 cells with regard to proliferation and gene expression of typical GCNIS/seminoma and differentiation markers." (PMID 31130628, 2019). "During further differentiation, FOXA2, SOX17, pluripotency and seminoma markers are downregulated." (PMID 31130628, 2019). "In summary, we provide evidence that FOXA2 induces the direct differentiation of seminoma-like TCam-2 cells into non-seminomatous cells in vivo." (PMID 31130628, 2019). "Additionally, strong and comparable expression of the seminoma and pluripotency markers OCT3/4, NANOG, LIN28, SOX17, PRAME, PRDM1/BLIMP1 and TFAP2C was found in TCam-2, TCam-2-ΔSOX2 and TCam-2-ΔSOX2/FOXA2 cells." (PMID 31130628, 2019). "Additionally, FOXA2 expression is not detectable in seminomas, ECs, teratomas, mixed GCTs and normal testis tissues (NTT)." (PMID 31130628, 2019).
seminoma (continued). "Thus, we postulate that FOXA2 is only upregulated during differentiation of seminomas into non-seminomatous lineages and downregulated once adaptation to the newly acquired cell fate is completed." (PMID 31130628, 2019). "This is in line with absent expression of FOXA2 in non-seminomas." (PMID 31130628, 2019). "Expression of typical seminoma markers (PRDM1/BLIMP1, SOX17, PRAME, TFAP2C) was also detectable in TCam-2-ΔSOX2/FOXA2 tumor tissues, in contrast to EC reprogramming factors (GDF3, DPPA3, DNMT3B, GAL), which could only be detected in 2102EP in vivo or reprogrammed TCam-2 cells." (PMID 31130628, 2019).
teratoma (6 papers, 2014 to 2023). A non-seminomatous germ cell tumor characterized by the presence of various tissues which correspond to the different germinal layers (endoderm, mesoderm, and ectoderm). "Three germ layer derivatives were also observed in the teratoma by immunofluorescent staining with three germ layer markers, Foxa2 for endoderm, α-actinin and α-SMA for mesoderm, Tuj1 and GFAP for ectoderm." (PMID 33608671, 2021). "A large number of cells staining positive for the endodermal marker forkhead box protein A2 (FOXA2) was found in all teratomas, with some also containing gland-like structures consisting of cells that contained AFP." (PMID 26777057, 2016). "Intestinal epithelium (endoderm tissue) expressing CDX-2 developed in the teratoma; some of these tissues also showed HNF3β/FOXA2 immunoreactivity (data not shown)." (PMID 25111735, 2014).
thyroid cancer (6 papers, 2008 to 2024). "Distinct roles of Foxa1 and Foxa2 are also consistent with our findings in C cell-derived thyroid cancer, suggesting that part of the developmental program is recapitulated in a tumor context." (PMID 26395490, 2015). "This showed that both FOXA1 and FOXA2 transcripts were enriched in MTC compared with thyroid cancer of follicular cell origin." (PMID 26395490, 2015). "Our present study demonstrated that forced expression of either HNF3β/FoxA2 or TTF-1 was unable to induce differentiation of the thyroid cancer cells as measured by NIS mRNA expression and radioiodine uptake." (PMID 18682709, 2008). "In summary, we found that the thyroid cancer cells had decreased the expression of TTF-1 and HNF3β/FoxA2; and their forced re-expression was associated with decreased cell growth." (PMID 18682709, 2008). "Here, we report for the first time that the presence of aberrant methylation of HNF3β/FoxA2 in thyroid carcinoma cell lines, and forced expression of the gene, resulted in growth inhibition." (PMID 18682709, 2008). "Earlier studies using either the TG or TPO promoter found that they were activated by TTF-1 and HNF3β/FoxA2 in thyroid carcinoma cell lines." (PMID 18682709, 2008). "Taken together, these results suggest that the expression of the HNF3β/FoxA2 gene is epigenetically repressed in thyroid carcinoma cell lines." (PMID 18682709, 2008). "It changed the expression of several genes, with an increase in some genes that are abnormally expressed in thyroid cancer such as ATP-binding cassette subfamily G member 2 (ABCG2), c-Myc (MYC), and forkhead box protein A2 (FOXA2)." (PMID 34439207, 2021). "Real-time PCR showed that HNF3β/FoxA2, TTF-1, and Pax-8 were expressed in normal thyroid tissue; in contrast, levels were either very low or undetectable in thyroid carcinoma cell lines." (PMID 18682709, 2008). "In addition, FOXA2 can inhibit PKM2 transcription, affect Wnt/β-catenin protein activity, and block the aerobic glycolysis of thyroid cancer." (PMID 38605023, 2024). "High expression levels of FOXA1 and FOXA2 were also evident in a RET-mutant MTC cell line (TT) but not in established lines from other types of thyroid carcinoma." (PMID 26395490, 2015). "Furthermore, dysregulation of three transcription factors (TTF-1, hepatocyte nuclear factor 3 β (HNF3β)/forkhead box A2 (FoxA2), and CCAAT/enhancer binding protein β (C/EBPβ)) was examined in thyroid carcinoma cells." (PMID 18682709, 2008).
yolk sac tumor (6 papers, 2019 to 2026). A non-seminomatous malignant germ cell tumor composed of primitive germ cells. "FOXA2 has been recognized as a master regulator for tumor formation in both yolk sac tumors of germ cell origin and somatic carcinomas with yolk sac tumor/enteroblastic differentiation (yolk sac‐like tumor)." (PMID 41001168, 2025). "There is significant overlap of somatically derived yolk sac‐like tumor and yolk sac tumor of germ cell origin beyond morphology, including expression of the master regulators of the yolk sac tumor phenotype (FOXA2) and, in some cases, miR‐371a‐3p." (PMID 41001168, 2025). "These entities can also be distinguished immunohistochemically, as yolk sac tumors are SALL4- and FOXA2-positive, while choriocarcinomas show beta-hCG expression." (PMID 41230344, 2025). "FOXA2 and SRRM2 are potential biomarkers for yolk sac tumors and Alzheimer’s disease." (PMID 41013561, 2025). "Tissues were also stained for CDX2, SOX2 and FOXA2, which were negative in accordance with the absence of yolk sac tumors (YST) and EC." (PMID 38097681, 2024).
Hepatic fibrosis (5 papers, 2017 to 2023). The presence of excessive fibrous connective tissue in the liver. "Of note, we found that at MH stage, loss of FOXA2 led to a significant increase in the expression of mRNA levels of genes associated with hepatic fibrosis and HSC activation, such as PDGF, MMP2, TGFβ2, TGFβ3, TGFβR2, and DLK1 among others." (PMID 35973994, 2022). "Either lentivirus LV-CMV-FOXA2 mediated FOXA2 overexpression in the liver or adeno-associated virus AAV8-TBG-FOXA2-mediated hepatocyte-specific upregulation of FOXA2 alleviated hepatic fibrosis." (PMID 29138513, 2017). "Together, these findings indicated that progressive liver fibrosis is associated with decreased FOXA2 expression." (PMID 29138513, 2017). "Taken together, these findings indicate that loss of FOXA2 may promote the activation of the HSCs, which subsequently enhances hepatic fibrosis." (PMID 35973994, 2022). "The protective effect of FOXA2 against CCL4-induced hepatic fibrosis in mice, was attributed to FOXA2 downregulation in hepatocytes." (PMID 35907883, 2022). "We have shown a decrease in the expression of LL35 lncRNA in liver fibrosis, which correlates with the previously published data for mRNA Foxa2." (PMID 31720018, 2019). "Overexpression of FOXA2 attenuates liver fibrosis by protecting hepatocytes from ER stress and apoptosis, thus suggesting that restoring hepatocyte integrity by FOXA2 has therapeutic potential for treating chronic liver diseases." (PMID 29138513, 2017). "As expected, FOXA2 also significantly declined in mouse livers during the progression of hepatic fibrosis, a result consistent with alterations in humans." (PMID 29138513, 2017). "Together, these data indicated that hepatocyte-specific excision of FOXA2 promotes liver fibrosis in mice." (PMID 29138513, 2017). "In this study, we generated mutant mice in which FOXA2 was specifically deleted in hepatocytes and demonstrated that FOXA2 knockout in hepatocytes exacerbated liver fibrosis induced by CCl4." (PMID 29138513, 2017). "To explore the role of FOXA2 in hepatic fibrosis, we first examined FOXA2 expression levels in the livers of 8 human controls and 30 patients with liver fibrosis or cirrhosis by using RT-PCR." (PMID 29138513, 2017). "Collectively, these data indicated that FOXA2 may play distinct biological roles in hepatocytes and HSCs during hepatic fibrosis." (PMID 29138513, 2017). "In conclusion, our findings suggested that FOXA2-mediated hepatocyte protection has a therapeutic role in hepatic fibrosis, and thus may be a new, promising anti-fibrotic option for treating chronic liver diseases." (PMID 29138513, 2017). "Furthermore, overexpression of FOXA2 in either the liver or hepatocytes markedly alleviated hepatic apoptosis and liver fibrosis." (PMID 29138513, 2017). "Hepatocyte-specific ablation of FOXA2 in adult mice exacerbated liver fibrosis induced by CCl4." (PMID 29138513, 2017). "Because deletion of FOXA2 in hepatocytes exacerbates the development of hepatic fibrosis, we wondered how FOXA2 upregulation might affect liver fibrosis." (PMID 29138513, 2017). "Additionally, by using three distinct viruses to deliver the expression of FOXA2 into the liver, we found that FOXA2 attenuated liver fibrosis by protecting hepatocytes from endoplasmic reticulum stress (ER stress) and apoptosis." (PMID 29138513, 2017). "Thus, the effects of FOXA2 expression on liver fibrosis induced by biliary injury also needs further investigation." (PMID 29138513, 2017). "Moreover, Foxa2 overexpression in the liver can reportedly alleviate hepatic fibrosis." (PMID 38144457, 2023). "RNA-sequencing analysis further validated the findings by showing a significant increase in genes associated with lipid metabolism, bile acid secretion, and suggested the activation of hepatic stellate cells and hepatic fibrosis in MH lacking FOXA2." (PMID 35973994, 2022). "However, there is no direct evidence showing a relationship between FOXA2 and liver fibrosis." (PMID 29138513, 2017).
neuroendocrine small cell carcinomas (5 papers, 2007 to 2025). "Recently, FoxA2 was demonstrated to be a sensitive and specific marker for small cell neuroendocrine carcinoma diagnosis." (PMID 39103560, 2024). "Furthermore, LNCaP with FOXA2 OE grew xenograft tumors much more rapidly than the control cells, showing mixed adenocarcinoma to small-cell carcinoma histology and strong synaptophysin (SYP) staining that closely recapitulated treatment-induced NEPC in patients." (PMID 40691407, 2025). "FOXA2 has been reported to be upregulated in NEPC and small cell neuroendocrine carcinomas." (PMID 39470735, 2024).
pancreatic ductal adenocarcinoma (5 papers, 2011 to 2024). An infiltrating adenocarcinoma that arises from the epithelial cells of the pancreas. "FoxA1 and FoxA2 were found to be expressed in most stages of pancreatic ductal adenocarcinoma progression." (PMID 39103560, 2024). "Although FOXA2 was regarded to suppress EMT during pancreatic ductal adenocarcinoma malignant progression, genomic analyses depicted that pancreatic progenitor tumors preferentially express genes involved in early pancreatic development (FOXA2)." (PMID 38252148, 2024). "Observations that Foxa2 may enhance stemness and tumorigenicity and suppress epithelial-to-mesenchymal transition in pancreatic ductal adenocarcinoma (PDAC) cells suggest that Foxa2 may play different roles at multiple stages of tumorigenesis." (PMID 37796967, 2023). "In contrast, FOXA1 and FOXA2 are positive regulators of E-cadherin, which suppress the EMT in pancreatic ductal adenocarcinoma." (PMID 21687740, 2011).